PABPC4L (poly(A) binding protein cytoplasmic 4 like)
Description:
May bind RNA.
Tractability: PROTAC: ubiquitination databases record sites on it.
Gene: Protein-coding gene on chromosome 4 (134,196,333 to 134,201,885, reverse strand). Ensembl gene ENSG00000254535.
Gene Ontology:
Molecular function: mRNA 3'-UTR binding; poly(U) RNA binding; nucleic acid binding; poly(A) binding; RNA binding
Biological process: oocyte maturation; positive regulation of gene expression
Cellular component: cytoplasmic stress granule; cytosol; nucleus; ribonucleoprotein complex
Genetic constraint (gnomAD): Loss-of-function variants: 2 observed, 0.91 expected, observed/expected ratio (o/e) 2.2. That is too few expected variants to judge how well the gene tolerates losing a copy. Missense variants: 452 observed, 448.42 expected, observed/expected ratio (o/e) 1.01, 90% interval 0.93 to 1.09. Synonymous variants: 169 observed, 157.35 expected, observed/expected ratio (o/e) 1.07, 90% interval 0.95 to 1.22.
Homologues: Orthologues: macaque PABPC4L (95% identical), rabbit PABPC4L (89% identical), chimpanzee PABPC4L (88% identical), pig PABPC4L (84% identical), rat Pabpc4l (82% identical), mouse Pabpc4l (81% identical), guinea pig PABPC4L (78% identical), dog PABPC4L (74% identical). Paralogues in human: PABPC4 (75% identical), PABPC1 (72% identical), PABPC3 (68% identical), PABPC1L (64% identical), PABPC5 (61% identical), PABPC1L2A (34% identical), PABPC1L2B (34% identical), PUF60 (19% identical), RBMS1 (19% identical), SYNCRIP (19% identical), RBMS3 (18% identical), RBMS2 (18% identical), and 12 more.
Diseases named in the same sentence as PABPC4L in open-access papers:
PABPC4L is named in the same sentence as 5 diseases in open-access papers, as found by Europe PMC text mining. Sharing a sentence is not in itself a finding about the gene and the disease. The quoted sentences say what the papers report.
ovarian carcinoma (1 paper, 2017). A malignant neoplasm originating from the surface ovarian epithelium. "The top predicted CNV regions associated with risk included FGFR1OP2 (RR=0.20, P=5 × 10−4) and PABPC4L (RR=0.22, P=0.006) for breast and ovarian cancer, respectively." (PMID 28145423, 2017).
parkinsonian disease (1 paper, 2019). "We identified a rare variant (c.C811T; p.R271X) in PABPC4L segregating in a family with atypical parkinsonian disease." (PMID 31537871, 2019).
cancer (3 papers, 2022 to 2025). A tumor composed of atypical neoplastic, often pleomorphic cells that invade other tissues. "We also found five genes discovered by the consensus DEA and PCA and annotated as candidate cancer genes in NCG: AJAP1, CD1B, CDH2, PABPC4L, and PCDH10." (PMID 40788820, 2025).
PABPC4L also shares sentences with these, for which no sentence is quoted: depression (1 paper); parkinsonian disorder (1).